IGF1R (insulin like growth factor 1 receptor)
Diseases named in the same sentence as IGF1R in open-access papers (continued):
Sharing a sentence is not in itself a finding about the gene and the disease.
breast cancer (continued). "In patients who did not receive tamoxifen, we did not observe an association between either PIK3CA mutation status, HER2, IGF-1R expression, or PTEN status and breast cancer prognosis." (PMID 24467828, 2014). "The possibility of targeting mTORC1 and other signaling pathways such as Raf/MEK/ERK, PI3K, IGF-1R to treat breast cancer is also being examined." (PMID 25051360, 2014). "It was first reported in 1994 that chromosome 15q26, where the insulin-like growth factor 1 receptor (IGF1R) is located, was amplified in <10% of breast cancers." (PMID 24392142, 2014). "Estradiol (E2) stimulated protein expression and phosphorylation of Shp2, and induced Shp2 binding to ERα and IGF-1R around the membrane to facilitate the phosphorylation of Erk and Akt in breast cancer cells MCF7." (PMID 25048202, 2014). "S6K1 overexpression has been found in high-grade breast cancers and when co-expressed with IGF1R it has been related to poor survival in all breast cancer subtypes." (PMID 25362932, 2014). "Our study covered three SNPs (IGF1R rs2654981, NFAT5 rs7359387, NELF rs1059111) that were previously studied in the context of breast cancer risk." (PMID 25003827, 2014). "Increased mTOR activity was suggested as a mechanism of resistance to IGF-1R inhibition in Ewing's Sarcoma as well as in a case of acquired resistance to HER2 receptor inhibitor lapatinib in breast cancer." (PMID 25344862, 2014). "Both in vitro and in vivo studies have shown that mammary tumors induced by IGF1R have weak metastatic capacity and that lowered expression of IGF1R is essential for increased cell motility." (PMID 25362932, 2014). "Ectopic expression of miR-375 inhibited IGF1R expression and restored sensitivity of breast cancer cells to trastuzumab." (PMID 24571711, 2014). "Targeting IGF-1R in multiple myeloma and breast cancer indicated a decrease in the formation of tumors and a diminuation of angiogenesis." (PMID 25095896, 2014). "Several clinical trials evaluating MK0646 and other IGF1R monoclonal antibodies in patients with various types of solid tumors, including breast cancer are nearing a conclusion or already completed." (PMID 24979294, 2014). "A reverse correlation between the levels of miR-375 and IGF1R was validated in clinical breast cancers." (PMID 24571711, 2014). "When comparing the CSC frequency of different populations of breast cancer cells, high expression of IGF-1R seems to be most efficient in enriching BCSCs in a triple negative breast cancer BC0244 xenograft (one out of 909 cells)." (PMID 23663564, 2013). "We recently demonstrated that human protein tyrosine phosphatase (PTP) L1, a large cytoplasmic phosphatase also known as PTP-BAS/PTPN13/PTP-1E, is a negativeregulator of IGF-1R/IRS-1/Akt path-way in breast cancer cells." (PMID 23514123, 2013). "It has in fact been shown in MCF7, MDA-231 and MDA-468 breast cancer cells that treatment with leptin can phosphorylate IGF1R and activate downstream signaling while treatment with IGF1 phosphorylates leptin receptor and activates downstream signaling." (PMID 24260287, 2013). "The study indicated that this technique can be used to monitor IGF-1R expression in breast cancer therapy and predict therapy response in individual patients." (PMID 23533377, 2013). "Elucidation of the role of IGF-1R in BCSCs is crucial to the design of breast cancer therapies targeting BCSCs." (PMID 23663564, 2013). "The expression rates of HER2 and EGFR in male breast cancer were comparable with recent findings, but other data for IGF1-R and MET in the male breast cancer literature are unavailable." (PMID 23308200, 2013). "Such a role for the IR in the context of targeted IGF1R has been demonstrated in a transgenic mouse model of pancreatic neuroendocrine carcinogenesis and human breast cancer cells, and in osteosarcoma cell lines." (PMID 23826179, 2013).
breast cancer (continued). "PTEN loss and expression of c-Kit, c-Met, HIF-1α, PDGFRA VEGFR2, and VEGF-A have been reported to be worse prognostic factors for breast cancer, whereas expression of IGF-1R, Bcl-2 and survivin are reportedly good prognostic factors for breast cancer." (PMID 24245483, 2013). "Emerging evidence suggests that signalling through the related IR provides a mechanism by which tumour cells resist the effects of IGF1-R inhibition in human osteosarcoma and breast cancer." (PMID 23826179, 2013). "IGF1R has also been shown to inhibit apoptosis induced by chemotherapeutic drugs in the HBL100 breast cancer cell line inferring chemo-resistance to the cancer cells." (PMID 24244833, 2013). "Taken together, IGF-1R inhibition not only decreased the CSC population of breast cancer but also suppressed the mammosphere formation and tumor growth of IGF-1R+ cells." (PMID 23663564, 2013). "Although the IGF-1/IGF-1R pathway seems to be important in breast cancer, its role in BCSCs remains to be delineated." (PMID 23663564, 2013). "In this study we demonstrate that hyperglycemia promotes breast cancer by altering leptin/IGF1R and AKT/mTOR signaling." (PMID 24260287, 2013). "Although many studies have demonstrated the efficacy of IGF1R inhibition for the treatment of breast cancer, little progress has been made in determining its effect for the prevention of breast cancer." (PMID 24069582, 2013). "In human breast cancer, of 41 different cell lines tested, only 7 were sensitive to the growth-inhibitory effects of an anti-IGF-1R antibody." (PMID 23548153, 2013). "Dysregulation of the insulin-like growth factor-1 receptor (IGF-1R)/phosphatidylinositol-3-kinase (PI3K)/Akt pathway was shown to correlate with breast cancer disease progression." (PMID 23663564, 2013). "Co-expression of IGF1-R with other growth factor receptors was comparable between male (15.7%) and female breast cancer (13.6%) (p = 0.187)." (PMID 23308200, 2013). "Inhibitors of signal molecules downstream of IGF-1R including PI3K/Akt/mTOR also reduced the ALDH+ population of breast cancer cells." (PMID 23663564, 2013). "MBS-784807 is a dual IGF-1R/InsR inhibitor that can synergize hormonal agents and has been shown to be a potential breast cancer drug." (PMID 24564956, 2013). "Growth factor receptors were variably expressed in 4.5% (MET) up to 38.5% (IGF1-R) of male breast cancers." (PMID 23308200, 2013). "These probes were reported to enter breast cancer cells overexpressing IGF-1R and then hybridize specifically with CCND1 mRNA to produce strong xenograft tumor signals." (PMID 23533377, 2013). "In this comprehensive systematic literature review and meta-analysis, we reported on expression prevalence of the hypoxia-related proteins GLUT1, CAIX, CXCR4, and IGF1R in breast cancer and carcinoma in situ, benign breast disease and normal breast tissue." (PMID 24206539, 2013). "Taken together, our findings support the notion that IGF-1R signaling with activation of the downstream PI3K/Akt/mTOR pathway plays an important role in breast cancer progression by controlling both the maintenance of BCSCs and their EMT behavior." (PMID 23663564, 2013). "miR-7 was also observed to reduce the expression of several oncogenes including PAK1 (p21 activated kinase 1) and IGF-1R (insulin-like growth factor 1 receptor) in breast cancer and tongue squamous cell carcinoma (TSCC) cell lines respectively." (PMID 22876288, 2012). "Compared with normal breast tissue, IGF-1R expression is detected at very high frequency in breast cancer specimens." (PMID 22792362, 2012). "Ligand-dependent activation of the estrogen receptor (ER) as well as of the insulin-like growth factor type 1 (IGF1R) induces the proliferation of luminal breast cancer cells." (PMID 22799881, 2012). "Ongoing trials in advanced breast cancer evaluate the activity of different drug combinations with IGF-1R inhibitors." (PMID 22415797, 2012).
breast cancer (continued). "Several phase I trials assessing the safety of IGF-1R targeted agents demonstrated clinical activity in two advanced breast cancer patients receiving AVE 1642 and one treated by AMG 479 as single agent." (PMID 22415797, 2012). "MSM can be used to treat herceptin-resistant breast cancers because the resistance is induced by IGF-1R and MSM effectively controlled the expression of IGF-IR." (PMID 22485142, 2012). "The principal factors felt to mediate cancer risk from metabolic syndrome have included insulin resistance, high IGF1R signaling and higher tissue levels of estrogen (for breast cancer)." (PMID 23369448, 2012). "The expression of IGF-1R decreased in the entire breast cancer cell lines treated with 300 mM of MSM whereas it found unaltered in normal cell line MCF-10A." (PMID 22485142, 2012). "We can conclude that the main area of interest of using IGF-1R targeted agents in breast cancer is a combination strategy with endocrine treatment, HER2 and mTOR targeted agents." (PMID 22415797, 2012). "Many in vitro and in vivo studies provided substantial evidence that insulin-like growth factor (IGF) and the IGF-1R signaling pathway are the major regulators of growth, survival, migration and invasion in human breast cancer." (PMID 22792362, 2012). "Our results support that trastuzumab resistance mechanisms are related with deregulation of PTEN/PI3K/Akt/mTOR pathway, and/or EGFR and IGF1R overexpression in a subset of HER2-positive breast carcinomas." (PMID 22454081, 2012). "In breast carcinoma cells, an interaction between ERα and IGF-1R has been recognized to enhance proliferative activity." (PMID 23227519, 2012). "A breast cancer cell line ectopically expressing human wild-type IGF-1R, MCF7/IGF-1R, was established by retroviral transduction and colony selection." (PMID 21595894, 2011). "The insulin-like growth factor-1 receptor (IGF-1R) is a transmembrane TK receptor frequently expressed in human breast cancers." (PMID 22295219, 2011). "Both the IGF-1R and insulin receptor are activated and expressed at elevated levels in breast cancer." (PMID 21854628, 2011). "We propose that elevated IGF-1R signaling can be an important element of breast cancer antiestrogen resistance." (PMID 21595894, 2011). "IGF-1R signaling contributes to breast cancer progression and recurrence in part by increasing cell survival via mechanisms that include suppression of anoikis." (PMID 21854628, 2011). "Insulin-like growth factor 1 (IGF-1) receptor (IGF-1R) is phosphorylated in all breast cancer subtypes." (PMID 21595894, 2011). "Ectopic expression of IGF-1R in ER-positive MCF7 human breast cancer cells enhanced IGF-1R tyrosine kinase signaling in response to IGF-1 ligand stimulation." (PMID 21595894, 2011). "In tamoxifen-resistant breast cancer cells, IGF-1R is upregulated and acts upstream of estrogen-activated EGFR." (PMID 21595894, 2011). "This discrepancy in responses between the two breast cancer cell lines is attributed to the differences in relative cellular IGF-1R and IR expression." (PMID 21773024, 2011). "To elucidate the direct role of IGF-1R signaling in breast cancer antiestrogen resistance, we established an ER-positive human breast cancer cell line ectopically expressing human wild-type IGF-1R, MCF7/IGF-1R, with elevated IGF-1R tyrosine kinase activity." (PMID 21595894, 2011). "Clinically, IGF-1R is commonly overexpressed in primary breast tumors and phosphorylated in all breast cancer subtypes, correlating with poor survival." (PMID 21595894, 2011). "IGF-1R signaling is important for the survival of breast cancer cells and crosstalk between IGF-1R and EGFR signaling pathways have been implicated in the development of more aggressive disease." (PMID 21854628, 2011). "High IGF-1R expression has been observed in breast cancer cell lines and human tissue specimens, leading to increased activity of this pathway." (PMID 24212944, 2011).
breast cancer (continued). "For example, in a mouse model of basal breast cancer with activated Ras, Igf1r signaling is required for survival." (PMID 21646685, 2011). "Along the same lines, ErbB2 and IGF-1R heterodimers contributed to trastuzumab resistance in breast cancer cells." (PMID 22216158, 2011). "Such RTK crosstalk has also been observed for the human EGF receptor 2 (HER2), the target of trastuzumab in breast cancer, and preclinical studies indicate synergy with dual IGF-1R/HER2 targeting." (PMID 24212944, 2011). "IGF1R functions as an anti-apoptotic agent by enhancing cell survival, and has been found expressed in most breast cancer cell lines and highly over-expressed in most malignant tissues." (PMID 20302654, 2010). "IGF-1R has been shown to be expressed in the majority of human breast cancers with evidence of sporadic amplification in a small proportion of these cases." (PMID 20668531, 2010). "Here we show that hypermethylation of the DMR2 of IGF2 is specifically observed in ERBB2 positive breast cancers providing a new potential mechanistic link between IGF1R expression and ERBB2 status via IGF2 methylation status." (PMID 20338046, 2010). "Of the genes examined, only genetic variants in IGF1R and its adaptor protein IRS1 were associated with risk of breast cancer in BRCA1 carriers." (PMID 19843326, 2009). "The type I insulin-like growth factor receptor (IGF1R) is overexpressed by many breast cancer cell lines and high levels of IGF1 are associated with poor prognosis in breast cancer." (PMID 19536088, 2009). "The ability of AVE-1642-conjugated QDs and Alexa 680 to bind to MCF-7 cells, a breast cancer cell line that expresses high level of IGF1R, was also examined." (PMID 19491901, 2009). "There is therefore a strong rationale for why genetic variation in IGF1R and IRS1 would be important in breast cancer risk in BRCA1 carriers." (PMID 19843326, 2009). "Cell lysates from MCF7 human breast cancer cells, which have previously been shown to express IGF1R, were used as a positive control." (PMID 19536088, 2009). "The association of IRS-2 with tumor progression was first indicated by the finding that inhibition of the IGF-1R in ER- breast carcinoma cells, which express IRS-2 and lack or have decreased IRS-1 expression, does not inhibit tumor proliferation." (PMID 19534786, 2009). "Increased IGF-1R signalling is associated with an upregulation of extracellular proteases necessary for tumour cell invasion in lung and breast cancer, and suppression of IGF-1R in breast cancer decreases tumour metastasis in vivo." (PMID 18598360, 2008). "In several human breast cancer cell lines, addition of the IGF-1R inhibitor AG1024 to gefitinib reduced cell proliferation in an additive or synergistic fashion and enhanced the induction of apoptosis over levels achieved by gefitinib alone." (PMID 15987464, 2005). "CCN6-rich medium induces a decrease in IGF-1-stimulated IGF-1R phosphorylation in breast cancer cells, and then results in an inhibition of cellular proliferation." (PMID 16457688, 2005). "The data presented here support further research into breast cancer therapeutic strategies combining gefitinib with anti-IGF-1R agents." (PMID 15987464, 2005). "The results presented here show the effects of adding an anti-IGF-1R strategy to gefitinib treatment in human breast cancer cell lines chosen for their similar expression of IGF-1R but their different EGFR levels." (PMID 15987464, 2005). "A potential cotarget receptor in breast cancer is the insulin-like growth factor 1 receptor (IGF-1R)." (PMID 15987464, 2005). "Tyrphostin AG 1024, one selective inhibitor of IGF-1R, was used to evaluate effects on proliferation, radiosensitivity, and radiation-induced cell apoptosis in a human breast cancer cell line MCF-7." (PMID 11747348, 2001). "Therefore, IGF-1R is often used as a therapeutic target for prostate cancer, breast cancer, and melanoma." (PMID 39920417, 2025).
breast cancer (continued). "While IGF1R-targeted monotherapies showed limited cytotoxic effects, combining IGF1R inhibitors with oHSV led to a significant, albeit modest, increase in cytotoxicity across tested in vitro breast cancer (BC) and primary glioblastoma (GBM) cells and in vivo xenograft models." (PMID 41510300, 2025). "Furthermore, wogonin modulated the IGF‐1R/Akt pathway to exert a complementary anticancer impact within breast cancer when combined with doxorubicin." (PMID 41164269, 2025). "Similarly, in HER2+ breast cancer, IGF-1R cooperates with HER2/ERBB2 signaling to sustain downstream PI3K/AKT and MAPK activation, thereby undermining the efficacy of HER2-targeted agents such as trastuzumab." (PMID 41157306, 2025). "For instance, in breast cancer tissue, reduced miR-122 and elevated IGF-1R were identified." (PMID 41153350, 2025). "Notably, SP1 plays a crucial role in promoting proliferation in breast cancer cells by regulating the expression of insulin-like growth factor-I receptor (IGF1R)." (PMID 40884402, 2025). "Future modifications to siRNAs targeting IGF-1R may improve their effectiveness in downregulating IGF-1R and modulating anti-tumor immune responses, potentially offering new clinical approaches for treating mammary tumors expressing IGF-1R." (PMID 39273251, 2024). "Additionally, IGF1R quantum dots are suitable for focusing and in vitro tumor imaging of breast cancer cells." (PMID 39771506, 2024). "We report that low IGFBP7 gene expression identifies a subset of breast cancers for which the addition of ganitumab, an anti-IGF-1R monoclonal antibody, to neoadjuvant chemotherapy, substantially improved the pathological complete response rate compared to neoadjuvant chemotherapy alone." (PMID 39362991, 2024). "Additionally, this study highlighted the potential of the IGF-I axis in mobilizing pro-inflammatory cytokines, offering a new clinical approach for treating mammary tumors expressing IGF-1R." (PMID 39273251, 2024). "miRNAs can also regulate the crosstalk between HER2 and IGF1R signaling pathways in breast cancer." (PMID 39051060, 2024). "MiR-375 was predicted to target IGF1R in trastuzumab-resistant HER2+ breast cancer cells." (PMID 38088952, 2024). "Overall, these data suggested that CXCL1 might induce autophagy by regulating the IGF1/IGF1R signaling in breast cancer." (PMID 39394189, 2024). "Additionally, TAMs/CXCL1 silence improved paclitaxel chemosensitivity by suppressing autophagy in breast cancer mice xenografts, and clinical studies further linked CXCL1 to IGF1R/HMGB1 signaling, as well as shorter free survival of recurrence." (PMID 39394189, 2024). "Another phase 1/2 study is under way in patients with triple-negative or HER2-negative breast cancer to assess a conjugate of the alpha emitter actinium-225 with an insulin-like growth factor-1 receptor-targeting humanized monoclonal antibody (ClinicalTrials.gov identifier NCT03746431)." (PMID 38123789, 2024). "In breast cancer models, the IGF1R regulates the expression and localization of YAP, a major mediator of the Hippo pathway, while YAP expression in turn up-regulates IGF1, a crucial mechanism underlying breast cancer stem cell progression." (PMID 38892104, 2024). "Advanced diagnostics and biomarker research are also central to the utilization of quantum dots in breast cancer, focusing on the early detection of mutations, such as those in the BRCA1 gene, and the quantitative analysis of cancer-related proteins like IGF1R." (PMID 38730959, 2024). "The co-inhibition of HER-2 and IGF-1R inhibits the proliferation of HER-2+ breast cancer cells." (PMID 38406785, 2023). "However, to date, clinical studies of IGF1R antagonism in ER positive breast cancer have been disappointing." (PMID 36920947, 2023). "Interestingly, Smoothened protein was found to positively regulate IGF-1R levels in lymphoma and breast cancer cell lines by stabilizing it in plasma membrane lipid rafts and preventing its lysosomal targeting." (PMID 37474760, 2023).